DKC1 (dyskerin pseudouridine synthase 1)
Diseases named in the same sentence as DKC1 in open-access papers (continued):
Sharing a sentence is not in itself a finding about the gene and the disease.
lymph node metastasis (2 papers, 2015 to 2020). "Increased DKC1 expression was associated with high grade of TNM stage, additional lymph node metastasis, and poor prognosis of patients with CRC." (PMID 31857720, 2020). "The univariate COX regression analysis showed that DKC1 expression, TNM stage, and lymph node metastasis were all the important prognostic factors for the overall survival of patients with CRC." (PMID 31857720, 2020).
microcephaly (2 papers, 2021 to 2023). A congenital or acquired developmental disorder in which the circumference of the head is smaller than normal for the person's age and sex. "In particular, DKC1 is involved in the Xp28 and X-linked recessive dyskeratosis congenita, known as a profound type of dyskeratosis congenita, including growth retardation and microcephaly." (PMID 37408531, 2023). "Most likely not, because in both publications cited above mutation DKC1 c.-142C>G is described in patients with dyskeratosis with no mentioned microcephaly." (PMID 33921653, 2021).
myeloid malignancies (2 papers, 2023 to 2025). "Patient 33 was suspected to have a TBD due to a deletion of the DKC1 gene, but telomere length studies could not be completed to confirm the diagnosis before she passed away from an aggressive myeloid neoplasm." (PMID 40936482, 2025).
Obesity (2 papers, 2022 to 2024). Accumulation of substantial excess body fat. "It is worth noting that UTP14A, DKC1, and PinX1 are all closely associated with angiogenesis in various diseases, so we speculate that all three may affect cardiac angiogenesis in obesity, but their angiogenic roles in cardiac tissue remain unclear." (PMID 35734237, 2022). "We found that six genes (Sacm1l, Junb, Bmi1, Erbb4, Dkc1, and Suv39h1) are neuron stress-related genes and increased in the HFD-induced mice obesity model, Bmi1gene was identified as a key genes that can reflect the pathophysiology of obesity." (PMID 39717104, 2024). "UTP14A, DKC1, DDX10, PinX1, and ESF1 may be involved in obesity-induced cardiac injury by affecting angiogenesis in the heart." (PMID 35734237, 2022). "UTP14A, DKC1, DDX10, PinX1, and ESF1 have been identified as hub genes in obesity-induced pathological changes in the heart and may be involved in obesity-induced cardiac injury by affecting cardiac microcirculatory function." (PMID 35734237, 2022).
osteosarcoma (2 papers, 2017 to 2023). A usually aggressive malignant bone-forming mesenchymal neoplasm, predominantly affecting adolescents and young adults. "To investigate in more detail the primary effects triggered by dyskerin loss‐of‐function phenotype, we generated colon carcinoma (RKO) and osteosarcoma (U2OS) stable cell lines expressing a short hairpin RNA (shRNA) able to trigger inducible silencing of the DKC1 gene." (PMID 28979836, 2017).
pulmonary disease (2 papers, 2021 to 2023). "DKC1 was known as a gene-encoded protein dyskerin and affected several modules of the telomere complex in pulmonary disease." (PMID 34366885, 2021).
renal carcinoma (2 papers, 2020 to 2023). A carcinoma arising from the epithelium of the renal parenchyma or the renal pelvis. "According to our findings, the expression of PUS1, PUS7, DKC1 and RPUSD1 is highly expressed in most cancer types, and among those genes, the expression of PUS1, PUS7 and RPUSD1 is markedly upregulated in renal cancers, including KICH, KIRC and KIRP." (PMID 37315299, 2023).
/T-cell lymphoma (1 paper, 2022). "It has indeed been shown that the miR-150 target gene repertoire can highly differ between different hematopoietic malignancies, e.g., MYB, FLT3, CBL and EGR2 in MLL-rearranged AML cells, and DKC1 and AKT2 in NK/T-cell lymphoma." (PMID 35205272, 2022).
aplastic anaemia (1 paper, 2011). "The incidence of aplastic anaemia is greater in patients with TERC or TINF2 mutations compared to patients with DKC1 mutations, and cancer incidence is highest in patients with TERC mutations." (PMID 21931702, 2011).
autism (1 paper, 2025). Persistent deficits in social interaction and communication and interaction as well as a markedly restricted repertoire of activity and interest as well as repetitive patterns of behavior. "In VPA females’ model of autism, nooclerin exerted the most pronounced influence on alterations in the transcriptional activities of the tnks genes, telomerase (Tep1, Dkc1) and the shelterin complex (Terf2ip, Pot1a, Tinf2, Tpp1, Trf1 - 2) in the hippocampus." (PMID 40272729, 2025).
bladder cancer (1 paper, 2020). "In sum, LINC01116 recruited DKC1 to stabilize the mRNA of a tumor-promoter HOXD8 in bladder cancer." (PMID 33311496, 2020).
brain tumour (1 paper, 2014). "For example, a decrease in expression of c-MYC, TIN2, DKC1, and RFC1 genes which are positive regulators of telomerase, was seen in MST-312 treated brain tumour cells." (PMID 25307264, 2014).
cervical adenocarcinoma (1 paper, 2023). An adenocarcinoma arising from the cervical epithelium. "In addition, Cervical Adenocarcinoma has the second highest alteration frequency of DKC1 (> 6%)." (PMID 38082360, 2023).
cervical cancer (1 paper, 2017). A primary or metastatic malignant neoplasm involving the cervix. "DKC1 has not been described to be associated with cervical cancer." (PMID 29312619, 2017).
cholestasis (1 paper, 2023). Impairment of the bile flow caused by obstruction within the liver, or outside the liver in the bile duct system.
cystic fibrosis (1 paper, 2025). Autosomal recessive disorder caused by pathogenic variants in the CFTR gene (cystic fibrosis transmembrane conductance regulator), which encodes a chloride and bicarbonate channel expressed in epithelial cells, and follow the diagnosis criteria. "Lastly, snRNA-H/ACA box snoRNA fusions (U>Ψ snRNAs) increase targeted RNA pseudouridylation without DKC1 overexpression, facilitating improved CFTR rescue from nonsense-mediated mRNA decay in a cystic fibrosis human bronchial epithelial cell model." (PMID 40968292, 2025).
diabetes (1 paper, 2025). "Age, diabetes, and hypertension had no impact on DKC1 expression." (PMID 40458122, 2025).
ectodermal dysplasia (1 paper, 2025). "In addition, genes such as TTC7A, SKIV2L, TTC37, and DKC1 also play a role in epithelial maintenance, with their defects often leading to ectodermal dysplasia, dysmorphism, and intestinal epithelial damage." (PMID 40474095, 2025).
endometriosis (1 paper, 2020). The growth of functional endometrial tissue in anatomic sites outside the uterine body. "Contrastingly, dyskerin (DKC1) mRNA and protein levels were unperturbed in the secretory phase eutopic endometrium of women with endometriosis." (PMID 33317189, 2020). "Our study examined hTERC and DKC1 expression levels in eutopic endometrium of women with endometriosis demonstrating significantly higher hTERC RNA in the secretory phase compared with healthy secretory endometrium." (PMID 33317189, 2020). "Considering all these previous data, we selected secretory phase endometrium of women with and without endometriosis to examine endometriosis associated differences in hTERC and DKC1 RNA levels using qPCR and dyskerin protein with IHC." (PMID 33317189, 2020). "Therefore, our aim was initially to examine the levels of hTERC and DKC1 RNA as well as dyskerin protein levels in normal endometrial tissue obtained from healthy women and in endometria collected from those with a surgical diagnosis of benign proliferative endometrial disease, endometriosis." (PMID 33317189, 2020). "Our novel finding that hTERC RNA levels are significantly higher in eutopic endometrial samples in the secretory phase of women with endometriosis, without altered levels of DKC1 mRNA, seems interesting." (PMID 33317189, 2020). "Consistent with experimental data, mid-secretory expression of DKC1 in mid-secretory endometrium from women with endometriosis was not significantly different when compared with the control healthy samples according to published datasets." (PMID 33317189, 2020).
epilepsy (1 paper, 2024). A brain disorder characterized by episodes of abnormally increased neuronal discharge resulting in transient episodes of sensory or motor neurological dysfunction, or psychic dysfunction. "Additional seizure- and epilepsy-associated proteins identified in PTE+ and PTE− cortex and hippocampus include Scnb1, Isca2, Wdr4, and Dkc1." (PMID 38474127, 2024).
esophageal cancer (1 paper, 2024). A primary or metastatic malignant neoplasm involving the esophagus. "This study aimed to examine the impact of the cuproptosis-associated gene DKC1 on the malignant progression of esophageal cancer." (PMID 39103487, 2024). "We confirmed that DKC1 is highly expressed in esophageal cancer tissues and cells through in vivo and in vitro experiments and that DKC1 expression is associated with poor patient prognosis." (PMID 39103487, 2024). "We validated the prognostic value of DKC1 in esophageal cancer patients and found that patients with high DKC1 expression had a worse prognosis than those with low DKC1 expression." (PMID 39103487, 2024). "Ultimately, the increased expression of DKC1 in esophageal cancer tissues was verified using clinical tissue samples." (PMID 39103487, 2024). "In this study, we identified a copper death-related gene, DKC1, in esophageal cancer." (PMID 39103487, 2024). "Finally, the involvement of DKC1 in the progression of esophageal cancer was investigated through in vivo and in vitro experiments." (PMID 39103487, 2024). "We also found that DKC1 promotes the proliferation and metastasis of esophageal cancer cells." (PMID 39103487, 2024). "Furthermore, DKC1-mediated promotion of esophageal cancer cell proliferation and migration was confirmed through both in vitro and in vivo experiments." (PMID 39103487, 2024).
interstitial lung disease (1 paper, 2021). A diverse group of lung diseases that affect the lung parenchyma. "Mutations in a number of telomere-related genes, including TINIF2, nuclear assembly factor 1 (NAF1), dyskerin pseudouridine synthase 1 (DKC1) and regulator of telomere elongation helicase 1 (RTEL1), have been identified and associated with IPF and other interstitial lung diseases (ILDs)." (PMID 33865386, 2021).
leukaemias (1 paper, 2015). "In X-linked DC, DKC1 deficiency predispose to cancer development, particularly skin cancers and leukaemias, by failing to stabilize telomerase and allowing cell proliferation in the absence of functional telomeres." (PMID 26366868, 2015).
metastatic colorectal cancer (1 paper, 2021). "However, the CITED2 and DKC1 genes were not reported in the metastatic colorectal cancer samples (MSKCC, Cancer Cell 2018, 1134 samples)." (PMID 34830168, 2021).
myeloma (1 paper, 2015). "Significant differences were observed for DKC1 in MM (p ≤0.026), suggesting an important role for this gene in the maintenance of short telomeres by telomerase in myeloma plasma cells." (PMID 26366868, 2015).
Pan (1 paper, 2023). "Furthermore, we checked the expression data of DKC1 from TCGA Pan Cancer database, integrated it with Tumor Mutational Burn and calculated the Spearman correlation." (PMID 38082360, 2023).
pancreatic cancer (1 paper, 2025). "A study found that METTL3-mediated m6A modification can significantly affect circCEACAM5 expression, which in turn promotes pancreatic cancer progression through activation of the DKC1 signaling pathway." (PMID 40458727, 2025).
Pancytopenia (1 paper, 2016). An abnormal reduction in numbers of all blood cell types (red blood cells, white blood cells, and platelets).
rectal cancer (1 paper, 2019). A primary or metastatic malignant neoplasm that affects the rectum. "In this report, we describe a patient with a DKC1 missense variant, c.361A>G (p.Ser121Gly), who developed multiple rectal cancers in young adulthood after bone marrow failure." (PMID 31027506, 2019). "In order to pursue further causes, whole-transcriptome analysis of frozen rectal cancer samples of the patient was conducted to elucidate the characteristics of the tumors, and the missense variant c.361A>G (p.Ser121Gly) in the DKC1 gene on chromosome X was detected." (PMID 31027506, 2019).
Viral infection (1 paper, 2021). "Viral infection affected host factors that regulate pseudouridine modification, downregulating DKC1 (also called Cbf5), PUS1, PUS3, and RPUSD2 (also called PUS9), as shown in one of six transcriptome experiments, each." (PMID 34502037, 2021).
X-linked adrenoleukodystrophy (1 paper, 2006). X-linked adrenoleukodystrophy (X-ALD) is a peroxisomal disorder resulting in cerebral demyelination, axonal dysfunction in the spinal cord leading to spastic paraplegia, adrenal insufficiency and in some cases testicular insufficiency.
cancer (81 papers, 2009 to 2026). A tumor composed of atypical neoplastic, often pleomorphic cells that invade other tissues. "Intriguingly, a recent study showed that cancer development mediated by telomere shortening due to mutations in DKC1 or other telomerase-related genes resulted from compromised immune surveillance but not genomic instability." (PMID 40458122, 2025). "By systematically investigating the aberrant expression of the DKC1 gene in cancers, it is possible to elucidate the mechanisms underlying the role of this gene in cancer." (PMID 39103487, 2024). "In this study, we conducted a systematic analysis of DKC1 and its regulatory factors and experimentally validated its excellent diagnostic and prognostic abilities in various cancers." (PMID 39103487, 2024). "For example, mutations in the snoRNA-associated pseudouridine synthetase DKC1 (dyskerin) cause X-linked dyskeratosis congenita, which is associated with bone marrow failure, skin and mucosa alterations, and increased cancer susceptibility." (PMID 37635368, 2023). "Our findings suggest that the precise expression of DKC1 is closely associated with the occurrence and developmental stages of cancer in multiple tissues." (PMID 38082360, 2023). "Recent reports showed that dysregulated expression of DKC1 in various human cancers alters cancer cell growth or metastasis and is associated with patient prognosis." (PMID 33879171, 2021). "Yet, while mutations and expression alterations in DKC1 have been significantly reported in cancer, little has been reported on the status of other Ψ synthetases." (PMID 33461542, 2021). "Increased expression of vascular endothelial growth factor has been associated to loss of DKC1, resulting their depletion in high incidence of cancer development." (PMID 33461542, 2021). "DKC1 dysregulation is associated with a high incidence of cancers in DC patients (reduced DKC1) and in DKC1 hypomorphic mice, but no reports are available of DC associated with EC." (PMID 33450922, 2021). "Despite the significant association of DKC1 activity or expression alterations to cancer, little is known on the role of other pseudouridylases and only few studies have associated alterations on their expression or activity to cancer." (PMID 33461542, 2021). "Excessive telomere shortening in Xq28, where the X-linked gene DKC1 (Dyskerin) is located, leads to genetic instability and high cancer risk." (PMID 28955657, 2017). "Point mutations in DKC1 gene cause the X-linked form of dyskeratosis congenital, a disease with increased predisposition to cancer." (PMID 28666010, 2017). "Patients with mutations in the DKC1 gene, which causes X-DC, exhibit an increased susceptibility to cancer among other abnormalities." (PMID 27252909, 2016). "At first glance, the finding that DKC1 is overexpressed in common carcinomas seems somewhat paradoxical, given that dyskerin-inactivating mutations in dyskeratosis congenita predispose to cancer development, and DKC1 is downregulated in sporadic CLL." (PMID 19755982, 2009). "However, certain snoRNAs and modification sites appear more “sensitive” to DKC1 mutations or changes in its expression levels, as observed in samples from dyskeratosis patients and cancer cells." (PMID 41510246, 2025). "The results showed that in most cases, DKC1 is a risk factor for various cancers." (PMID 39103487, 2024). "To investigate whether DKC1 is involved in the immune infiltration process in cancer, we assessed the associations between DKC1 and major histocompatibility complex (MHC) molecules, immune checkpoint genes, immune activation genes, and chemokines." (PMID 39103487, 2024). "Genetic mutations in DKC1 inactivate keratin and lead to congenital dyskeratosis, which is characterized by skin defects, hematopoietic dysfunction and increased susceptibility to cancer." (PMID 37426487, 2023). "However, a positive correlation between DKC1 expression and cancer-associated fibroblasts was found in KIRP, KIRC, and MESO." (PMID 38082360, 2023).